TIA1 (TIA1 cytotoxic granule associated RNA binding protein)
Diseases named in the same sentence as TIA1 in open-access papers (continued):
Sharing a sentence is not in itself a finding about the gene and the disease.
Alzheimer disease (13 papers, 2014 to 2026). A progressive, neurodegenerative disease characterized by loss of function and death of nerve cells in several areas of the brain leading to loss of cognitive function such as memory and language. "Tia1 mRNA is detectable in the mouse brain during embryogenesis, and is linked to the pathophysiology of neurodegeneration, e.g., Alzheimer′ s disease." (PMID 34572124, 2021). "Recent research has identified TIA-1 as a key player in neurodegenerative diseases, especially those involving Tau pathology such as in Alzheimer’s disease (AD), in a subtype-dependent manner." (PMID 41877170, 2026). "Cytoplasmic aggregates containing SFPQ and TIA1 have also been observed in an in vivo Alzheimer’s disease model." (PMID 38668381, 2024). "Evidence has demonstrated that Tia1 is a potential biomarker in the brain of a mouse model for Alzheimer′s disease." (PMID 34572124, 2021). "Impressive recent work has shown that reducing levels of TIA1 or ataxin-2 delays disease progression in models for Alzheimer's disease (AD) or ALS, respectively, further supporting the importance of RBPs in neurodegenerative diseases." (PMID 31138677, 2019). "TIA‐1 has also been shown to interact with Tau inclusions in mouse models of Alzheimer's disease and in post‐mortem patient tissues." (PMID 28377462, 2017). "The role of TIA1 has been implicated in several neurological diseases including ALS, Alzheimer’s disease and Frontotemporal Lobar Dementia79." (PMID 28775379, 2017). "A SG marker and nucleating protein TIA-1 has also been found in Alzheimer’s disease neurofibrillary tangles, composed of hyperphosphorylated and aggregated Tau, in increasing amounts with increasing disease severity." (PMID 27460788, 2016). "Interestingly, Wdfy1 level upregulation and Tia1 dysregulation were among the 16 most promising biomarkers that characterized the brain of mouse model of Alzheimer’s disease, with Wdfy1 showing the changes earlier than Tia1." (PMID 24659297, 2014). "Thus, TIA1 ablation differentially affects gene expression in brain of males and females, suggesting that TIA1 may serve as a gender-specific modifier of several neurological diseases such as ALS, Alzheimer’s disease and frontotemporal lobar dementia." (PMID 30533021, 2018).
viral infection (10 papers, 2012 to 2024). "Virus infection also results in the formation of classic TIA1/G3BP1-positive stress granules due to viral protein synthesis and replication." (PMID 33952639, 2021). "Since the replication of the viral genome occurs at around 8 h after infection, these results showed that the suppression of HDGF and TIA-1 began during the early and late phases of viral infection, respectively." (PMID 25275311, 2014). "The observation that the SG marker TIA-1 showed a punctate distribution at the early stages of virus infection, but was filamentous/tubular distribution at later times, suggests that it was re-distributed into the Golgi-derived filamentous/tubular compartments." (PMID 32605035, 2020). "Furthermore, the aggregates differed from the stress granules induced by viral infection in their failure to colocalize with SG markers such as TIA1 and to recruit endogenous RIG-I." (PMID 31710640, 2019). "Therefore, VA RNAs suppressed HDGF expression under the conditions other than viral infection, and a smaller amount of VA RNA than TIA-1 was sufficient to suppress HDGF." (PMID 25275311, 2014). "The mammalian homolog of UBP1b is TIA-1, an RNA binding protein localized to the nucleus that moves into the cytoplasm and aggregates into stress granules upon induction of stresses such as treatment with arsenite, glucose deprivation, and viral infection." (PMID 22346759, 2012). "In contrast, TIA-1 translocated from the nuclei to the cytoplasm and formed aggregates co-localizing with G3BP during viral infection, which was similar to the results after sodium arsenite (AS) stimulation." (PMID 29518158, 2018). "Interestingly, a number of viral infections have been described to trigger the formation of small discrete “stress granules” instead of canonical SGs, based on the inclusion of G3BP, PABP, TIA1, and/or poly(A) in those assemblies (29, –, 32)." (PMID 31896577, 2020). "This restrictive effect of TIA-1 has been described for VSV and for several other viral infections." (PMID 27749929, 2016). "Together with the Ras-GAP SH3 domain binding protein (G3BP), T-cell restricted intracellular antigen 1 (TIA-1), and TIA-1-related protein (TIAR), these aggregates form stress granules (SGs) to stall translation and protect the cell from accumulating misfolded proteins during viral infections." (PMID 31213553, 2019). "However, mivaRNAs suppress TIA-1 expression only during the late phase and have never been detected during the early phase of viral infection." (PMID 25275311, 2014). "Similarly, although TIA1 is recruited into SGs during viral infection, RABV-induced SGs do not require TIA-1 for their formation, as the SGs are formed efficiently in the absence of TIA-1 after infection of TIA-1-/- MEFs or si-TIA-1-treated U373-MG cells." (PMID 27749929, 2016).
/T-cell lymphoma (7 papers, 2012 to 2025). "For NK/T-cell lymphomas, markers like CD2, cytoplasmic CD3, CD56, and cytotoxic granules (granzyme B, perforin, TIA-1) are typically positive." (PMID 41367858, 2025). "Immunohistochemical analyses demonstrated the expression of CD2, CD3, CD56, TIA-1 and EBER, consistent with the immunophenotype of extranodal NK/T-cell lymphoma, nasal type." (PMID 25013513, 2014). "On the other hand, the findings of cytotoxicity-associated molecule TIA-1+, no TCR rearrangement and EBV + could indicate NK/T-cell lymphoma." (PMID 22931631, 2012). "The current case demonstrated the immuno characteristics of tumor cells are typical nasal-type NK/T cell lymphoma: CD3+, CD56+, TIA1+, Perforin+, Granzyme B+." (PMID 24886075, 2014). "Though clonal T-cell receptor gene rearrangement has been reported in 7–38% of extranodal NK/T-cell lymphoma cases, in the absence of CD56, CD8, TIA1, and granzyme B made extranodal NK/T-cell lymphoma, nasal type an unlikely diagnosis." (PMID 25143841, 2014). "In contrast, the findings of TIA-1+, EBER1+ and no TCR rearrangement could indicate NK/T-cell lymphoma." (PMID 22931631, 2012). "Based on overall findings, a diagnosis of CD30 and EBV positive T-cell lymphoma primarily involving the subcutaneous tissue was confirmed which could be best classified as PTCL, NOS in terms of the absence of TIA1 and granzyme B expression and the presence of EBV infection." (PMID 25143841, 2014).
distal myopathy (7 papers, 2018 to 2024). Distal myopathy refers to a group of muscle diseases which share the clinical pattern of predominant weakness and atrophy beginning in the feet and/or hands. "While TIA1- and SQSTM1/TIA1-associated distal myopathy display a rather identical clinical phenotype compared to MATR3 (in terms of onset, muscle weakness and histopathology), none of these disease entities typically include a relevant dysphagia and dysphonia." (PMID 32361838, 2020). "Furthermore, respective changes were not present in MR-studies from patients with MYOT- and SQSTM1/TIA1-associated distal myopathy overseen in the neuromuscular research centre in Halle." (PMID 32361838, 2020). "Genetic modifiers likely play a role, such as the synergistic effect of TIA1 (c.1070A > G, p.Asn357Ser) and SQSTM1 mutations affecting the UBA domain, resulting in distal myopathy." (PMID 36861178, 2023). "The recently reported digenic distal myopathy caused by a SQSTM1 mutation and a variant in the PrD protein TIA1 further demonstrates how a combined effect of variants in PQC and client proteins together can determine the phenotypic outcome." (PMID 32093037, 2020). "In contrast, relevant similarities were observed in 6 distal myopathies (TIA1, late-stage TTN, MYOT, SQSTM1/TIA1, KLHL9, ADSSL1)." (PMID 32361838, 2020). "We present the first detailed clinical and pathologic data from three unrelated families with predominant distal myopathy associated with a known pathologic variant in SQSTM1 (p.Pro392Leu) and a variant in TIA1 (p.Asn357Ser)." (PMID 29599744, 2018). "Some patients with a distal myopathy with rimmed vacuolar pathology resembling WDM but lacking disease-causing mutations in TIA1 were found to have a common TIA1 polymorphism." (PMID 39501809, 2024). "Additionally, gluteal and paraspinal changes as observed in MATR3-myopathy were not seen in whole-body examination of a patient with SQSTM1/TIA1-associated distal myopathy, a distal myopathy that displays similar lower limb findings as compared to MATR3-associated myopathy." (PMID 32361838, 2020).
melanoma (6 papers, 2006 to 2024). A malignant, usually aggressive tumor composed of atypical, neoplastic melanocytes. "TIA-1+ cells have also been described in medullary breast cancer and melanoma, where they are associated with favorable prognostic features." (PMID 19641607, 2009). "This is noteworthy as TIA‐1 is a protein associated with granules in cytotoxic T cells and a decrease in the percentage of TIA‐1+ tumor infiltrating leukocytes has been shown to correlate with tumor progression in malignant melanoma." (PMID 35790025, 2022). "TIA-1 (a lytic granule associated protein whose over expression before rIL-2 therapy but not after has been linked to the immune responsiveness of melanoma metastases) was down-regulated in accordance to others' in vitro experimental findings." (PMID 16805915, 2006). "Although in melanoma the presence of the retinoblastoma binding (RB) mRNA Rbfox2 in SGs was associated with progression and metastasis, the presence of TIA1, G3BP1, and TIAL1 in melanoma-derived SGs has not been reported, so new experimental approaches would be needed." (PMID 39594467, 2024). "In melanoma patients, peritumoral injection of IFN-β also recruits effector cells, including CD8 and TIA1-positive cytotoxic T cells (CTLs), into the tumor microenvironment, which suggests a possible mechanism for the therapeutic effects of IFN-β in the treatment of melanoma." (PMID 29050354, 2017).
pancreatic cancer (5 papers, 2011 to 2024). "Splicing factors (SRSF1, EIF3B, TIA1) are implicated in the enrichment of pancreatic cancer-derived exosomal miRNA, particularly contributing to the exosome shuttling of miR-1246." (PMID 38419074, 2024). "Loss of TIA-1 expression promoted the tumorigenesis and aggressive behavior of pancreatic cancer cells." (PMID 35776220, 2022). "Considering that curcumin treated cells were actively transiting through mitosis before undergoing mitotic catastrophe, it further implies that inducing CUGBP2 and TIA-1 might be an effective chemotherapeutic strategy to treat pancreatic cancer cells." (PMID 21347286, 2011). "Using a labeled miR-1246 probe as “bait”, we fished out several RBPs from pancreatic cancer cells, including serine and arginine rich splicing factor 1 (SRSF1), eukaryotic translation initiation factor 3 subunit B (eIF3B), and T cell-restricted intracellular antigen 1 (TIA1)." (PMID 32819370, 2020).
colon cancer (4 papers, 2016 to 2025). "Alternative splicing of TIA-1 in human colon cancer can regulate VEGF isoform expression, angiogenesis, tumor growth, and bevacizumab resistance." (PMID 35252219, 2021). "Also defective binding of TIA-1 to COX-2 mRNA has been reported to increase COX-2 expression in colon cancer cells." (PMID 27271770, 2016). "Furthermore, binding of TIA-1 to the proximal region of the 3′-UTR of COX-2 following IL-1β has also been demonstrated by electrophoretic mobility shift assay (EMSA) in renal mesangial cells and defective RNA binding of TIA-1 has been shown to promote COX-2 expression in colon cancer cells." (PMID 29555582, 2018).
gastric cancer (4 papers, 2017 to 2022). A primary or metastatic malignant neoplasm involving the stomach. "TIA-1 levels were reduced by miR-19a and miR-487a in breast and gastric cancers, respectively, thereby promoting cell migration and invasion." (PMID 35776220, 2022). "For example, TIA1 inhibits progression of gastric cancer by suppressing tumor cell proliferation and accelerating apoptosis, whereas it serves as an oncogene in esophageal squamous cell carcinoma through promoting cell proliferation." (PMID 32984057, 2020). "Similar TIA1 protein decreases were also observed in lung cancer (LC) tissues and gastric cancer (GC) tissues." (PMID 28257633, 2017). "Among these splicing factors, TIA1 and NOVA1 have been proven to promote gastric cancer development via regulating AS." (PMID 33281863, 2020).
Obesity (4 papers, 2016 to 2022). Accumulation of substantial excess body fat. "Our results and those of others suggest that a molecular link could exist between aging-dependent aberrant expression of TIA1 and/or TIAR and obesity-associated deleterious phenotypes." (PMID 30533021, 2018). "Furthermore, TIA1 expression may be a better marker of obesity in females than in males, because downregulation of several genes in TIA1-knockout female brain may contribute to body weight gain, as the nervous system partly controls body weight." (PMID 30533021, 2018). "Since ox-LDL is a typical biomarker for oxidative stress in HFD-induced obesity and related metabolic syndromes, we next used ox-LDL to treat primary peritoneal macrophages from WT and Pdcd4-/- mice, and examined TIA-1+ SGs in these macrophages." (PMID 27454120, 2016). "Our results suggest that the downregulation of TIA1 expression may be a better marker of obesity in females rather than in males." (PMID 28775379, 2017).
ovarian carcinoma (4 papers, 2009 to 2025). A malignant neoplasm originating from the surface ovarian epithelium. "Moreover, lncRNA CRNDE increased SRSF1 expression and subsequently elevated TIA1 expression, which caused cisplatin resistance in ovarian cancer." (PMID 36105363, 2022). "For example, CRNDE inducing cisplatin resistance through SRSF1/TIA1 signaling pathway in ovarian cancer." (PMID 40176901, 2025).
Arthritis (3 papers, 2016 to 2022). Inflammation of a joint. "By contrast, TIA1-depleted adult mice present middle-age arthritis, abnormal macrophage physiology and increased susceptibility to endotoxin shock, but with normal hematopoietic and immune system phenotypes." (PMID 30533021, 2018). "Moreover, TIA1-KO mice develop spontaneous arthritis, associated with pathological overexpression of TNF-α." (PMID 35163320, 2022). "Experiments in several mouse strains revealed that in the absence of TIA1, 46% of mice died between E16.5 and 3 weeks of age, and surviving mice had no apparent major abnormalities other than an arthritis-associated phenotype." (PMID 35163320, 2022).
bladder cancer (3 papers, 2022 to 2025). "Overall, these results are consistent with a BCG-associated attenuation of aerobic glycolysis in bladder cancer cells that depends, at least in part, on TIA1." (PMID 41300366, 2025). "Subsequent step-wise multivariate regression distilled the model to four independent predictors—NPM1 (HR = 1.42), RUNX2 (HR = 1.25), TET1 (HR = 1.41), and TIA1 (HR = 0.67)—thereby establishing a concise LLPS-related signature for risk stratification in bladder cancer." (PMID 41300366, 2025). "Collectively, these results demonstrate that TIA1 suppresses the glycolytic program in bladder cancer cells, and that this repression is largely dependent on its low-complexity domain and condensate-forming capacity." (PMID 41300366, 2025). "This positions TIA1 as a candidate RNA-binding protein linking metabolic RNA handling to immune-relevant outputs in bladder cancer, consistent with the broader condensate literature." (PMID 41300366, 2025). "Spatial transcriptomics analysis of four adjacent sections from a human bladder carcinoma further underscored the link between TIA1 and cytotoxic immunity." (PMID 41300366, 2025). "Second, the upstream signals that modulate TIA1 condensation in bladder cancer remain undefined; cytokine- or hypoxia-driven phosphorylation could alter phase behavior and merits investigation." (PMID 41300366, 2025). "To test whether TIA1 can directly modulate CD8+-cell function, we co-cultured CFSE-labeled human CD8+ T cells with T24 bladder cancer cells engineered for TIA1 gain- or loss-of-function." (PMID 41300366, 2025). "Collectively, our functional assays demonstrate that LLPS-impaired, domain-deletion TIA1 orchestrates a dual program of tumor glycolytic suppression and CD8+-T-cell activation, positioning TIA1 as a link that may integrate metabolic control with anti-tumor immunity in bladder cancer." (PMID 41300366, 2025). "In preliminary studies, we found that the expression levels of the classic proto-oncogenes, IGF2BP1, MYC, LIN28B and STAT3 in bladder cancer T24 cells were higher than those in normal cells, while the expression levels of the tumor suppressor genes FTO and TIA1 were negligible in T24 cells." (PMID 35288535, 2022). "Given our finding that condensate-competent TIA1 is a potent brake on glycolysis, we asked whether BCG could exploit the same axis to impose a metabolic ‘checkpoint’ on bladder cancer cells, thereby creating a micro-environment conducive to subsequent CD8+-T-cell attack." (PMID 41300366, 2025).
breast carcinoma (3 papers, 2019 to 2025). "We also note that the expression of BRCA1 and Xist are inversely correlated in breast cancer cell lines, raising the possibility that changes in BRCA1 activity might underlie the increased Xist expression in the TIA1+/− cells." (PMID 31875547, 2019). "LINC00894 enhances cell proliferation and invasion by binding with miR-429 to mediate ZEB1 expression in breast cancer (Meng, Shao & Feng, 2021); what’s more, in thyroid cancer, its increased expression reduces the oncogenic properties by sponging let-7e−5p to promote TIA-1 expression." (PMID 36570012, 2022).
Cerebral ischemia (3 papers, 2016 to 2023). Restriction of arterial blood supply to the brain associated with insufficient oxygenation to support the metabolic requirements of the tissue. "Our previous research demonstrates that the marker of stress granules [T-cell intracellular antigen 1 (TIA1)] is upregulated at the early time-points of blood reperfusion after 2 h of cerebral ischemia, accompanying a significant decrease of apoptosis level in the ischemic cortex." (PMID 32982696, 2020). "In line with this, our study found that expressions of G3BP1, TIA1, and DDX3X33, 52 and the major components of SGs were transiently increased at 0 h after cerebral ischemia/reperfusion, and then decreased gradually until 24 h postreperfusion." (PMID 37580991, 2023). "TIA-1 and TIAR are upregulated in hypoxia in a model of rat brain ischemia, and form stress granules mediating HIF repression." (PMID 27141964, 2016).
esophageal squamous cell carcinoma (3 papers, 2016 to 2022). Esophageal squamous cell carcinoma (ESCC) is a type of esophageal carcinoma (EC) that can affect any part of the esophagus, but is usually located in the upper or middle third. "Here, we report previously unknown tumor-promoting activity of TIA1, which seems to be associated with its isoform-specific molecular distribution and regulation of a set of cancer-related transcripts, in esophageal squamous cell carcinoma (ESCC)." (PMID 26958940, 2016).
glioblastoma (3 papers, 2010 to 2025). The most malignant astrocytic tumor (WHO grade IV). "In glioblastoma, levels of the RBP cytotoxic granule-associated RNA-binding protein (TIA1) (Drosophila: Rox8) increase following YAP knockdown to prevent cell invasion in U87 glioblastoma cells." (PMID 35735914, 2022). "In the present study, we show that the cytoplasmic QKI isoforms, QKI-6 and QKI-7, but not nuclear isoform (QKI-5), localize with Ago2, PABP1, and TIA1 within stress granules in the U343 glioblastoma cell line and in primary rat oligodendrocytes." (PMID 20862255, 2010).